OR10B1P (olfactory receptor family 10 subfamily B member 1 pseudogene)
Synonyms: OR10B2
Gene: Unprocessed pseudogene on chromosome 19 (15,141,105 to 15,142,062, reverse strand). Ensembl gene ENSG00000267961.
Diseases named in the same sentence as OR10B1P in open-access papers:
OR10B1P is named in the same sentence as 1 disease in open-access papers, as found by Europe PMC text mining. Sharing a sentence is not in itself a finding about the gene and the disease.
OR10B1P shares sentences with these, for which no sentence is quoted: infection (2 papers).